SMPD1 (sphingomyelin phosphodiesterase 1)
Diseases named in the same sentence as SMPD1 in open-access papers (continued):
Sharing a sentence is not in itself a finding about the gene and the disease.
Sepsis (17 papers, 2015 to 2024). Sepsis is defined as life-threatening organ dysfunction caused by a dysregulated host response to infection. "The activity of the conserved stress enzyme sphingomyelin phosphodiesterase 1 (SMPD1) has been shown to be elevated in sepsis patients, allowing for risk stratification." (PMID 30326559, 2018). "This study determined the degree and the potential role to which SMPD1 and its modulation affect sepsis-induced cardiomyopathy using both genetically deficient and pharmacologically-treated animals in a polymicrobial sepsis model." (PMID 28420138, 2017). "Our aim was to clarify the role of tissue specific ceramide generation during sepsis and additionally to find whether the enhanced generation is caused by SMPD1 as a common cardiac link also relevant in patients with heart failure." (PMID 28420138, 2017). "Abnormal splicing of acidic sphingomyelinase 1 (SMPD1) mRNA is known to result in altered enzyme activity and an impact on the development of sepsis." (PMID 38727856, 2024). "In the present study, we intended to investigate the impact of the stress responsive enzyme acid sphingomyelinase (SMPD1) on regulation of hepatic CYP expression and activities during sepsis using SMPD1 heterozygous animals relative to wild-type littermates." (PMID 30326559, 2018). "In conclusion, partial genetic inhibition of SMPD1 stabilizes hepatic ceramide content and improves hepatic monooxygenase function in the acute phase of polymicrobial sepsis." (PMID 30326559, 2018). "In the course of endotoxemia and Staphylococcus aureus induced sepsis, functional inhibition of SMPD1 exerted protective effects and improved survival rates." (PMID 30326559, 2018). "Transcriptional expression rate on the other hand was still downregulated in SMPD1+/+ mice, confirming a long-term impact of polymirobial sepsis on hepatic function in sepsis survivors." (PMID 30326559, 2018). "The transcriptional expression of (A) Cyp1a1, (B) Cyp2a5, (C) Cyp3a11 was significantly downregulated in SMPD1+/+ mice at 24 h following sepsis induction." (PMID 30326559, 2018). "In the acute phase of sepsis, SMPD1+/+ mice showed an increased hepatic C16- as well as C18-ceramide content." (PMID 30326559, 2018). "Induction of polymicrobial sepsis in SMPD1+/− littermates, in contrast, resulted in a diminished reduction of expression levels as compared to SMPD1+/+ mice (0.38 (IQR 25%: −0.47 and IQR 75%: 1.34) log2 fold change; p ≤ 0.05)." (PMID 30326559, 2018). "Previous studies demonstrated increased SMPD1 activity in patients with sepsis as well as with chronic heart failure, both correlating to disease severity." (PMID 28420138, 2017). "The plasma-secreted isoform of acid sphingomyelinase (SMPD1) is a conserved enzyme in cellular stress response playing a detrimental role in sepsis and remote organ failure." (PMID 28420138, 2017). "Overall, results from our study support the notion that an increased activity level of SMPD1 displays a detrimental role with respect to regulation of liver function in both the acute and post-acute phase of sepsis." (PMID 28955042, 2017). "Glutathione levels decreased significantly in untreated SMPD1+/+ at 24 h following sepsis as compared to corresponding baseline animals (baseline: 588.5 (IQR 496.3–687.8) vs. 451.1 (IQR 443.8–457.0) μg/g, p ≤ 0.05)." (PMID 28420138, 2017). "Acid sphingomyelinase (SMPD1)—the principal regulator for rapid and transient generation of the lipid mediator ceramide—is involved in both the regulation of host response in sepsis as well as in the pathogenesis of chronic heart failure." (PMID 28420138, 2017). "This study provides first evidence of a detrimental role of the conserved stress responsive enzyme SMPD1 in the development of sepsis-induced liver dysfunction and fibrosis, which both affect the outcome from sepsis and the quality of life in sepsis survivors." (PMID 28955042, 2017).
Sepsis (continued). "The GSH/GSSG ratio decreased in the untreated SMPD1+/+ group at 24 h following sepsis (baseline: 5.9 (IQR 5.7–6.2) vs. 5.3 (IQR 5.1–5.4), p ≤ 0.05) as well as in the untreated SMPD1−/− group (baseline: 6.0 (IQR 5.8–6.5) vs. 5.3 (IQR 4.5–5.3), p ≤ 0.05)." (PMID 28420138, 2017). "Pretreatment with desipramine resulted in significantly higher GSH/GSSG ratios in SMPD1−/− animals at 24 h following sepsis as compared to SMPD1+/+." (PMID 28420138, 2017). "In order to clarify the role of SMPD1 as a stress enzyme in sepsis-induced liver dysfunction, we used mice, which are partially deficient in the enzyme." (PMID 28955042, 2017). "It reflects large inter-individual differences even without any pathophysiological meaning and makes a quantitative classification of certain SMPD1 splice-events as population wide sepsis marker challenging." (PMID 25898364, 2015). "In terms of molecular differences in ASM expression between SIRS and severe sepsis/septic shock we analyzed the frequency of certain SMPD1 splice-isoforms separately." (PMID 25898364, 2015). "Sepsis-induced cardiac dysfunction, lung edema, and declined anti-inflammatory responses can be reversed by genetic ablation or pharmacological inhibition of sphingomyelin phosphodiesterase (SMPD1) and Sphk in septic rodents." (PMID 34087197, 2021). "Hepatic CYP1A activities, as assessed by EROD, showed a significant reduction of the values in SMPD1+/+ animals 24 h after sepsis induction from a median value of 203.3 (IQR 25%: 189.5 and IQR 75%: 245.6) pmol/(mg protein × min) to 112.5 (IQR 25%: 97.8 and IQR 75%: 126.9) pmol/(mg protein × min)." (PMID 30326559, 2018). "Furthermore, sepsis-associated pro-inflammatory cytokines, such as TNF-α, induce activation of SMPD1 and, subsequently, the formation of ceramide in primary isolated hepatocytes." (PMID 30326559, 2018). "In the present study, as an immediate surrogate for increased SMPD1 activity, liver tissue levels of C16- and C18-ceramide were increased in wild-type animals after sepsis induction, reflecting cellular stress response, whereas levels of C20-, C22- and C24-ceramide remained stable." (PMID 30326559, 2018). "At 24 h after sepsis induction, SMPD1+/+ animals displayed a significant decrease in enzyme activities (control: 291.9 (IQR 25%: 275.5 and IQR 75%: 348.8) pmol/(mg protein × min) vs. 24 h: 155.5 (IQR 25%: 99.2 and IQR 75%: 230.1) pmol/(mg protein × min); p ≤ 0.05)." (PMID 30326559, 2018). "However, our experiments were based on the observation that increased plasma levels of SMPD1 have been found in patients with sepsis as well as patients with chronic heart failure." (PMID 28420138, 2017). "Both SMPD1+/+ (baseline: 1.87 ± 0.68 vs. 1.12 ± 0.13, p ≤ 0.05) and SMPD1−/− animals (baseline: 1.79 ± 0.4 vs. 1.15 ± 0.37, p = 0.057) displayed a reduction of MV E/A at 6 h following polymicrobial sepsis as compared to baseline values." (PMID 28420138, 2017). "Among the plethora of pathophysiological changes in sepsis, the enhanced activity of the stress responsive enzyme sphingomyelin-phosphodiesterase 1 (SMPD1) might function as a promising target for therapeutic interventions." (PMID 28955042, 2017). "Here we show that the patterns of alternatively spliced SMPD1 transcripts are significantly different in patients with systemic inflammatory response syndrome and severe sepsis/septic shock compared to control subjects allowing discrimination of respective disease entity." (PMID 25898364, 2015). "In addition, SMPD1 is known to be differentially spliced in human sepsis." (PMID 37711610, 2023). "Thus, an association of specific pattern of alternatively spliced SMPD1 transcripts with disease severity (healthy and non-infectious patients undergoing intensive care as controls vs. sepsis) was observed." (PMID 33553211, 2020).
Sepsis (continued). "Since we were also able to show that the functional inhibitor of SMPD1, desipramine, ameliorates downregulation of CYP mRNA expression and activities in the acute phase of sepsis in wild-type mice, SMPD1 might be an interesting pharmacological target, which should be further investigated." (PMID 30326559, 2018). "As these SMPD1 inhibiting drugs are FDA-approved drug, which are frequently prescribed for neurological disorders, observational studies in well-defined patients could unravel, whether FIASMA use is associated with reduced liver injury in patients with sepsis." (PMID 28955042, 2017). "Interestingly, desipramine pretreatment of SMPD1−/− (612.0 (IQR 566.0–710.0) U/L, p ≤ 0.05) and SMPD1+/+ (610.0 (IQR 566.0–710.0) U/L, p ≤ 0.05) resulted in less pronounced elevation following sepsis induction as compared to untreated SMPD1+/+ animals (1395.0 (IQR 640.0–1885.0) U/L)." (PMID 28420138, 2017). "In our study, we expand the knowledge of a beneficial effect of SMPD1 inhibition by treating animals with desipramine 7 days prior and 6 hours following to severe infection, resulting in decreased SMPD1 activity thus followed by improved sepsis-induced oxidative stress." (PMID 28955042, 2017). "Fittingly, we were already able to demonstrate that SMPD1 heterozygous animals show less pronounced hepatic cytokine expression, which in turn might result in stabilization of SMPD1 activity as well as hepatic ceramide content and, therefore, inhibition of monooxygenase downregulation during sepsis." (PMID 30326559, 2018). "C16-ceramide significantly increased in myocardial tissue homogenates in SMPD1+/+ from 12,629 (IQR 8900–22,254) pmol/g at baseline vs. 60,140 (IQR 59,697–68,968) pmol/g following polymicrobial sepsis (p ≤ 0.05)." (PMID 28420138, 2017). "Since it is known that functional inhibitors of SMPD1, such as imipramine, are capable of reducing hepatic fibrosis, we were interested whether desipramine, also a functional inhibitor, is capable to reduce hepatic fibrosis occurring in sepsis survivors as a long-term sequela." (PMID 28955042, 2017). "In addition, Cyp3a11 expression showed a significant decrease of the median value in SMPD1+/+ animals from −0.05 (IQR 25%: −0.61 and IQR 75%: 0.59) log2 fold change to −2.65 (IQR 25%: −3.41 and IQR 75%: −1.45) log2 fold change following sepsis induction." (PMID 30326559, 2018). "dSMPD1+/+, as well as dSMPD1−/− displayed no changes during sepsis at both time points, respectively, and significantly higher values were shown at 6 h in dSMPD1+/+ (1.73 ± 0.1, p ≤ 0.05) as compared to SMPD1+/+ at a similar time point." (PMID 28420138, 2017). "Therefore, we investigated alternative splicing of SMPD1 transcripts in patients with SIRS and severe sepsis/septic shock to appoint molecular characteristics of ASM expression in human sepsis." (PMID 25898364, 2015). "Therefore, the aim of the present study was to investigate whether SMPD1 activity has an impact on expression and activity of different hepatic CYP enzymes using an animal model of polymicrobial sepsis." (PMID 30326559, 2018). "The expression rate of Cyp1a1 in SMPD1+/+ animals significantly decreased from a median control level set to 0.0 (IQR 25%: −0.08 and IQR 75%: 0.07) log2 fold change to −1.04 (IQR 25%: −1.83 and IQR 75%: −0.93) log2 fold change at 24 h following polymicrobial sepsis induction." (PMID 30326559, 2018). "In contrast, SMPD1+/− mice (control: 230.7 (IQR 25%: 179.3 and IQR 75%: 275.7) pmol/(mg protein × min) vs. 24 h: 153.9 (IQR 25%: 138.1 and IQR 75%: 184.0) pmol/(mg protein × min)) demonstrated a significantly smaller decline in CYP1A activity 24 h following sepsis induction." (PMID 30326559, 2018). "Pretreatment of SMPD1+/+ animals with desipramine resulted in significantly elevated baseline values (54,425 (IQR 59,697–68,968) pmol/g, p ≤ 0.05 vs. SMPD1+/+ at baseline), but abrogated the increase of ceramide generation following sepsis (77,879 (IQR 57,644–109,723) pmol/g)." (PMID 28420138, 2017).
Sepsis (continued). "In SMPD1+/− mice, however, no noticeable changes of ceramide content and CYP expression and activities during sepsis could be observed." (PMID 30326559, 2018). "However, desipramine pretreatment of SMPD1+/+ (baseline: 4.9 (IQR 4.5–5.6) vs. 5.4 (5.1–5.7), not significant (n.s.)) and SMPD1−/− animals (baseline: 5.4 (IQR 4.6–5.9) vs. 6.1 (IQR 5.4–6.9), n.s.)had no influence on the values during sepsis." (PMID 28420138, 2017).
endothelial dysfunction (14 papers, 2013 to 2025). In vascular diseases, endothelial dysfunction is a systemic pathological state of the endothelium (the inner lining of blood vessels) and can be broadly defined as an imbalance between vasodilating and vasoconstricting substances produced by (or acting on) the endothelium. "In summary, the present study demonstrated that EC-specific Smpd1 gene overexpression enhanced the production of ceramide and the formation of MR redox signaling platforms, promoted the activation of endothelial NLRP3 inflammasomes, and thereby resulted in endothelial dysfunction and atherogenesis." (PMID 36252682, 2022).
diabetes (13 papers, 2009 to 2025). "Consequently, the markedly different roles of miR-15a and SMPD1 in diabetes and AAA, as well as changes in levels of circulating miR-15a, could explain parts of the interplay between the two diseases." (PMID 40481348, 2025). "Low sphingomyelin could arise from higher aSMase (SMPD1) activity, and high levels of aSMase have been correlated with insulin resistance and diabetes." (PMID 34553271, 2021).
Alzheimer disease (11 papers, 2020 to 2025). A progressive, neurodegenerative disease characterized by loss of function and death of nerve cells in several areas of the brain leading to loss of cognitive function such as memory and language. "Of the genes with intragroup duplication, variants in SMPD1 have previously been shown to increase α-synuclein levels and impair acid sphingomyelinase trafficking to lysosomes to induce the development of Alzheimer’s disease." (PMID 37679557, 2024). "Indeed, while loss-of-function recessive variants in SMPD1 have been primarily related to NPD, recent studies suggest a connection between heterozygous SMPD1 variants and several other diseases such as Parkinson disease (PD) and Alzheimer disease (AD)." (PMID 33925997, 2021).
glioma (10 papers, 2015 to 2026). A benign or malignant brain and spinal cord tumor that arises from glial cells (astrocytes, oligodendrocytes, ependymal cells). "Ionizing radiation and TMZ, as current standard therapy for glioma patients, affect the sphingolipid pathway by activating SMPD1 which hydrolyzes sphingomyelin to pro-apoptotic ceramide." (PMID 39723240, 2024). "Recent preclinical research indicates that antidepressant fluoxetine (Prozac), a selective serotonin reuptake inhibitor (SSRI), can inhibit SMPD1 and induce cell death in glioma by accumulating sphingomyelin, which results in inhibition of oncogenic EGFR signaling and activating lysosomal stress." (PMID 39723240, 2024). "The converging axis involving sphingomyelinase and sphingosine-1-phosphate, mediated by the actions of sphingomyelinase SMPD1 and sphingosine-kinase SPHK1, emerged as a pivotal factor in glioma." (PMID 42144879, 2026).
Niemann-Pick disease type B (10 papers, 2013 to 2026). "Niemann–Pick type B disease shows some clinical and biochemically similarities to the type C disease, but is genetically different, in that the type B disease results from mutations in the SMPD1 gene, and deficiency in the enzyme activity of acid sphingomyelinase (EC:3.1.4.12)." (PMID 33506652, 2021).
Parkinson disease (9 papers, 2014 to 2025). A progressive degenerative disorder of the central nervous system characterized by loss of dopamine producing neurons in the substantia nigra and the presence of Lewy bodies in the substantia nigra and locus coeruleus. "One of the involved genes, SMPD1, had previously been reported to be mutated in patients with Parkinson's disease." (PMID 31595719, 2019). "Following the initial identification of the rare p.L302P mutation in SMPD1 as a strong risk factor for Parkinson’s disease in Ashkenazi Jews, two additional SMPD1 founder mutations were identified in this population." (PMID 30551571, 2018). "Although the pathogenic relationship between ASMD and Parkinson’s disease in this patient is unknown, it recently has been suggested that at least some SMPD1 mutations are associated with an increased risk of Parkinson’s disease." (PMID 28228103, 2017). "Given that heterozygous mutations in the Niemann-Pick disease gene SMPD1 have recently been associated with Parkinson’s disease, it is possible that similar mechanisms explain how mutations in other autophagy-lysosome genes increase Parkinson’s disease risk." (PMID 24574503, 2014). "Within this group, sphingolipidoses genes involved in glycosphingolipid breakdown are known (GBA1) or candidate (SMPD1, ASAH1) risk factors for Parkinson’s Disease, though disease mechanisms remain unclear." (PMID 41279717, 2025). "To see if a similar phenomenon exists also for C9orf72 intermediate repeats, we analyzed Parkinson’s disease patients of Ashkenazi origin, in a stratified manner, in carriers of mutations in LRRK2, GBA, and/or SMPD1 genes, and in patients that do not carry these mutations." (PMID 34440384, 2021).
multiple sclerosis (8 papers, 2017 to 2024). A progressive autoimmune disorder affecting the central nervous system resulting in demyelination. "On the other hand, deficiency of aSMase gene (SMPD1) enhanced myelin repair after cuprizone-induced demyelination in a mouse model used to examine myelin destruction and remyelination in multiple sclerosis." (PMID 32098196, 2020).
atherosclerosis (7 papers, 2009 to 2024). A disease characterized by the build-up of fatty material and calcium deposition in the arterial wall resulting in partial or complete occlusion of the arterial lumen. "This first demonstration of a p62/SQSTM1-dependent myofibroblast-like phenotypic transition in Smpd1−/− SMCs suggests that ASM-mediated autophagy pathway contributes to maintaining the arterial smooth muscle homeostasis in situation of vascular remodeling during atherosclerosis." (PMID 30451833, 2018).
ischemia (7 papers, 2013 to 2024). A hypoperfusion of the BLOOD through an organ or tissue caused by a PATHOLOGIC CONSTRICTION or obstruction of its BLOOD VESSELS, or an absence of BLOOD CIRCULATION. "To test, if effects of Smpd1−/− differ depending on the duration of ischemia, we evaluated Smpd1−/− mice exposed to 60 or 90 min of intraluminal MCAO." (PMID 33057972, 2020). "LDF measurements above the core of the middle cerebral artery territory revealed reproducible ischemia during MCAO in Smpd1+/+ and Smpd1−/− mice that was followed by the rapid recuperation of blood flow to baseline values after reperfusion onset." (PMID 33057972, 2020). "Neuroprotective effects of Smpd1−/− in ischemia durations shorter than 60 min and longer than 30 min cannot be excluded." (PMID 33057972, 2020). "The more severe ischemia (60 min vs. 30 min MCAO) very likely explains why they observed elevated sphingomyelinase activity, while we found reduced sphingomyelinase activity in reperfused brain tissue of Smpd1+/+ mice at the time-point of animal sacrifice." (PMID 33057972, 2020).
colitis (6 papers, 2019 to 2025). Inflammation of the colon. "For example, mice with deficiency of acid sphingomyelinase (ASMase; Sphingomyelin phosphodiesterase 1), the enzyme hydrolyzing SM to Cer and phosphorylcholine, are strongly susceptible to Citrobacter rodentium-driven colitis." (PMID 31867330, 2019).